CXCR4 (C-X-C motif chemokine receptor 4)
Diseases named in the same sentence as CXCR4 in open-access papers (continued):
Sharing a sentence is not in itself a finding about the gene and the disease.
tumor (continued). "To confirm that SDF-1α/CXCR4 signaling during wound healing affects tumor growth, we treated wounded or unwounded animals with a small molecule inhibitor of CXCR4, AMD3100, or the carrier DPBS from the day of wounding until euthanasia." (PMID 23593347, 2013). "The present study observed that a CXCR4-specific antagonist effectively inhibited CXCR4/Akt signal transduction in PC-3 cells, as well as tumor growth in nude mice challenged with PC-3 cells." (PMID 24137439, 2013). "It has also been shown that CXCR4 inhibition significantly reduces T-regulatory cell infiltration into the tumor while increasing antitumor immunity." (PMID 24384839, 2013). "Studies have shown that tumour cells that express CXCR4 preferentially metastasize to the bone, where its ligand, CXCL12, is abundantly expressed." (PMID 26237063, 2013). "For example, CXCR4 expression in tumor cells has been described to be attendant with oncogenic events such as hypoxia, RET/PTC mutations, EGFR variant-mediated invasion, and HER2 overexpression." (PMID 23484027, 2013). "The chemokine receptor CXCR4 contributes to tumor growth and the metastatic spread of several cancer entities." (PMID 23385555, 2013). "Its effect is mediated by interaction with CXC chemokine receptor-4 (CXCR4) which is the only physiologic receptor for SDF-1 known to play a role in tumor metastasis, chemotaxis, and other metastasis components." (PMID 23401782, 2013). "The tumor promoting effect of SDF-1/CXCR4 signaling has been well documented for a variety of epithelial and hematopoietic malignancies and inhibition of CXCR4 signaling has been shown to reduce tumor growth and metastasis." (PMID 23593347, 2013). "As such it appears that during tumor progression different CXCR4 positive cell populations exist within the tumor." (PMID 23326303, 2013). "CXCR4, together with its ligand CXCL12 (namely the CXCL12 / CXCR4 axis), is well known to be involved in many aspects of tumor progression, especially in tumor metastasis." (PMID 24312338, 2013). "The chemokine stromal cell-derived factor-1 (SDF-1) and its receptor C-X-C chemokine receptor type 4 (CXCR4) are considered the first identified and most notable substances involved in tumor cell migration." (PMID 23833663, 2013). "There is a clinical need for potent anti-metastatic CXCR4-antagonists with improved profile over existing ones, particularly, for frequent dosing required for persistent blockade of CXCR4-induced tumour metastasis." (PMID 24205302, 2013). "Several studies suggest that CXCR7 contributes to tumor progression indirectly via regulation of CXCR4-dependent activities." (PMID 23555768, 2013). "The CXCL12/CXCR4 axis was shown to be involved in tumor development and metastatic spread of many cancer types, including OS." (PMID 24040160, 2013). "It will be interesting to investigate what the influence of the presence of CXCR4++ cells will be on metastatic ability of metastatic MIN-O tumor models." (PMID 23326303, 2013). "MIF was expressed in the cytoplasm of tumor cells and TILs, and CXCR4 was expressed in the nucleus or cytoplasm and cell membrane of tumor cells and the cell membrane and cytoplasm of TILs." (PMID 23497377, 2013). "Overall, our data shows that emodin can significantly downregulate the expression of CXCR4, a key receptor involved in the crosstalk between tumor cells and its microenvironment, which contributes to its observed in vivo anti-metastatic effects." (PMID 23472074, 2013). "In an effort to determine the biological significance of Akt/CXCR4 axis in tumor growth, we subcutaneously implanted both low Akt1 (Neo) and high Akt1 (HA-Akt1) expressing cells in SCID mice." (PMID 23902739, 2013). "Clinical outcome in patients with high level expression of CXCR4 is significantly worse than in patients with low CXCR4 tumor expression." (PMID 24376734, 2013).
tumor (continued). "Mature miR-133b and CXCR4 expression levels were detected in 31 tumor samples and their adjacent, non-tumor tissues from patients with CRC, as well as in 6 CRC cell lines, using real-time quantitative RT-PCR (qRT-PCR)." (PMID 24330809, 2013). "High expression levels of MIF in tumor cells were not correlated with clinicopathological variables, whereas high expression levels of CXCR4 in tumor cells were positively closely correlated with T status (P = 0.045) and clinical stage (P = 0.044)." (PMID 23497377, 2013). "CXCR4 overexpression is known in more than 20 human tumour types, including ovarian, prostate, esophageal, melanoma, neuroblastoma." (PMID 23301946, 2013). "This has been well documented in breast cancer for the chemokine CXCL12 that, through interaction with its receptor CXCR4 in metastasizing tumor cells, directs their homing to the metastatic site." (PMID 24040160, 2013). "All SHH tumors demonstrate co-overexpression of CXCL12 and CXCR4, with the exception of one tumor that was obtained after treatment with high-dose chemotherapy." (PMID 23497290, 2013). "High MIF expression in tumor cells or in TILs or high CXCR4 expression in tumor cells was significantly related to poor survival of ESCC patients (P < 0.05)." (PMID 23497377, 2013). "Additional studies demonstrate that de novo expression of CXCR4 is sufficient to increase tumor invasion and metastasis in an organ-specific manner." (PMID 24259307, 2013). "The CXCL12/CXCR4/CXCR7 chemokine axis has been identified as an important element in tumor development, progress and metastasis." (PMID 24074251, 2013). "Based on the criteria described in the Methods section, high expression levels of MIF and CXCR4 in tumor cells were noted in samples from 73 (53.7%) and 47 (34.6%) of the 136 patients, respectively." (PMID 23497377, 2013). "Immunohistochemical analysis, showed strong CXCR4 expression in untreated tumor tissues and interestingly, emodin administered mice showed reduced staining thereby, indicating that emodin can suppress the expression of CXCR4 in HCC tissues." (PMID 23472074, 2013). "The SDF-1/CXCR4 (stromal cell derived factor 1/chemokine (C-X-C motif) receptor 4) pathway has been suggested to play a role in the metastatic dissemination of neoplasms with migration toward SDF-1 by tumor cells bearing CXCR4." (PMID 24376459, 2013). "PGK1 expression is significantly positively correlated with CXCR4 expression and tumor dissemination to the bone marrow." (PMID 24376734, 2013). "As expected, HA-Akt1 tumors have stronger Akt Serine 473 phosphorylation and CXCR4 expression, suggesting that Akt1 induced CXCR4 expression, contributing to the primary tumor growth." (PMID 23902739, 2013). "In our study, both IL4R and CXCR4 gene expressions were decreased with tumor progression, whereas both DOK2 and IL2RG gene expressions were increased with tumor progression." (PMID 23451142, 2013). "It has also been proposed that CXCR4 expression levels can be used to select subsets of tumor lesions that show a more aggressive biological behavior." (PMID 23326303, 2013). "The fluorescent label was used to assess the membranous CXCR4 expression pattern in fresh tumor segments obtained from tumor bearing mice." (PMID 23326303, 2013). "The statistical analysis showed a significant negative correlation between DFS, OS and the expression levels of MIF in tumor cells and TILs and CXCR4 in tumor cells (P < 0.05)." (PMID 23497377, 2013). "In agreement with their findings, our results from the intracranial xenograft model reveal that disrupting the CXCL12/CXCR4 pathway reduces both the vessels that sprout from the tumor core and the intratumoral microvessel density." (PMID 23961808, 2013). "CXCR4 promotes tumor progression at different levels of malignancy, including tumor growth, angiogenesis, metastatic dissemination, and homing in CXCL12-enriched cellular niches in metastatic tissues." (PMID 23497377, 2013).
tumor (continued). "Hypoxia induced by vascular disrupting agents produced an increase in tumor SDF-1 expression as well as increased infiltration of CXCR4+ TEMs." (PMID 23882218, 2013). "Previous studies also have reported that blocking CXCR4-dependent pathways in the tumor microenvironment is critical for therapeutic effects in cancer." (PMID 23372646, 2013). "We observed positive staining for CXCR4 in the nucleus of PCa tissues; furthermore, the amount of nuclei positively stained for CXCR4 increased with the grade of the tumor." (PMID 23468933, 2013). "Radiation-induced recruitment of TAMs appears to occur in a similar manner as that caused by tumor hypoxia, is partially dependent on the SDF-1/CXCR4 and CSF-1/CSFR signaling pathways, and promotes polarization toward the M2 phenotype." (PMID 23882218, 2013). "In contrast, CXCR4 protein expression significantly increased in 52.63% of CRC samples, and increased CXCR4 expression in CRC was associated with advanced tumor stage." (PMID 24330809, 2013). "Our results demonstrated that the miR-133b/CXCR4 pair is involved in tumor growth and tumor cell apoptosis and controls cell migration and invasion." (PMID 24330809, 2013). "This indicates that wound fluid derived SDF-1α mediates wound-promoted tumor growth by stimulating CXCR4-signaling in tumor cells." (PMID 23593347, 2013). "In analogy, CXCR4 expression has been found to characterize a subpopulation of the CD133+ pancreatic CSC that seem to be reponsible for the metastasis of the tumor." (PMID 24069258, 2013). "Although it is still unclear, that what leads to the overexpression of CXCR4 in different tumor cells, previous reports implicate the involvement of various genetic and epigenetic factors." (PMID 23472074, 2013). "Understanding the pathophysiology of the tumor microenvironment creates further avenues for treatment, such as a CXCR4 antibody that is currently in early development for a number of hematological malignancies." (PMID 23984125, 2013). "Since CXCR4 inhibition was reported to interfere with tumor cell growth, we evaluated the effects of peptides R, I, and S on the growth of subcutaneous human renal SN12C cells engineered to express green fluorescence protein (GFP)." (PMID 24058588, 2013). "Immunoblot analysis showed that emodin significantly suppressed the expression of CXCR4 in tumor tissue." (PMID 23472074, 2013). "Of direct relevance to our results, increased CXCR4 expression and CXCL12/ CXCR4 signaling promote tumor cell resistance to the chemotherapeutic gemcitabine." (PMID 23442791, 2013). "The 5 randomly selected gene expression changes observed using the Human Tumor Metastasis RT2 Profiler PCR array (CXCR4, CXCL12, MMP2, MMP9 and MMP13) were confirmed using qPCR." (PMID 24179538, 2013). "Multivariate analysis showed that the expression of MIF or CXCR4 in tumor cells and the expression of MIF in TILs were adverse independent factors for disease-free survival (DFS) and overall survival (OS) in the whole cohort of patients (P < 0.05)." (PMID 23497377, 2013). "Along these lines, the results of a recently reported study showed that CXCR7 enhanced CXCL12/CXCR4-mediated trans-endothelial migration of tumor cells." (PMID 24040160, 2013). "A significant correlation was also found between miR-133b and CXCR4 protein expression in tumor samples." (PMID 24330809, 2013). "Because, HER2 has been shown to induce the expression of CXCR4 in tumor cells, we also analyzed the expression levels of HER2 in these four HCC cells." (PMID 23472074, 2013). "In the present study, the protein expression levels of MIF and CXCR4 were examined in tumor specimens from 136 patients with ESCC." (PMID 23497377, 2013). "The subsequent CXCL12/CXCR4 signaling also enhances cell survival via Akt activation, thereby providing an advantage to newly arrived tumor cells in the bone microenvironment." (PMID 26237063, 2013).
tumor (continued). "But binding to the RBCs was blocked by coinjection of the tracer, also resulting in elevated accumulation in CXCR4 positive tumor." (PMID 22685650, 2012). "A significant correlation of HER2- and CXCR4-expression in primary tumor and metastases exists in the orthotopic model." (PMID 23082154, 2012). "Both SDF-1 and CXCR4 were expressed in the tumor core, with CXCR4 being primarily localized around necrotic areas and more scattered elsewhere." (PMID 22539956, 2012). "Further, the relationship between CXCR4 and tumor initiating cell markers CD133/CD44 is reciprocal: CXCR4+ cells have a higher percentage of CD133+/CD44+ than CXCR4− cells and CD133+/CD44+ cells contain more CXCR4+ cells than CD133−/CD44− cells." (PMID 22359577, 2012). "Our findings argue in favor of a specific role of CXCR4 expressed in stromal cells that conditioned the pro-tumor microenvironment." (PMID 22399057, 2012). "There is growing evidence that the SDF-1/CXCR4 axis is important for tumor proliferation, survival, vascularization and metastasis." (PMID 23039915, 2012). "Correspondingly, the western blotting analysis showed that the protein of CXCR4 expressed highly in tumor tissues from the grafted LLC mouse model." (PMID 23300882, 2012). "Knockdown of CXCR4 expression using small interfering RNA in BC cells decreases in vitro cell survival, invasion and proliferation and abrogates in vivo tumor growth." (PMID 22709548, 2012). "The X-tile program provided cut-points to divide tumours into low, moderate and high groups with H-score 0–60 (low; 11%), 60–115 (moderate; 20%) and 115–300 (high; 69%) for tumour CXCR4 expression." (PMID 22415233, 2012). "Whereas CXCR4 was solely expressed by tumor cells, CXCL12 was observed in both tumor and stromal areas." (PMID 23249693, 2012). "Chemokines such as CXCL1 and CXCL8 are able to enhance tumor cell proliferation; CXCL5 and CXCL12 attract neutrophils and MDSC, while CXCL12 promotes the migration of tumor cells that express the cognate receptor CXCR4." (PMID 22927846, 2012). "In particular, CXCR-4, which is associated with brain metastases in IBC, is stimulated by VEGF-A, linking VEGF-A expression to the migratory potential of tumor cells." (PMID 22813402, 2012). "The positive rate of CXCL12 protein was 13.3% (4/30), the positive rate of CXCR4 protein was 80% (24/30) in tumor tissues." (PMID 23181100, 2012). "There is evidence that blocking CXCR4 can inhibit the proliferation, invasion and metastasis of tumor cells." (PMID 23039915, 2012). "CXCR4 expression in tumor cells of several types of carcinomas is correlated with a poor prognosis, e.g. breast and prostate tumors." (PMID 22709548, 2012). "The unique function of CXCR4 is to promote the homing of tumor cells to their microenvironment at the distant organ sites." (PMID 22485156, 2012). "Our data clearly show anti-tumorigenic properties for the CXCR7 receptor in NB, as CXCR7 was able to affect in vitro migration-promoting effect mediated by the CXCR4/CXCL12 axis, and to delay orthotopic tumor take of CXCR4-positive NB cells." (PMID 22916293, 2012). "Considering that the inoculated cell line B16 expresses functional CXCR4 in both mice models, the results relied on a lower CXCR4 expression in the multiplicity of cells that form the tumor stroma." (PMID 22399057, 2012). "As anti-SDF-1 treatment counteracts this increased tumor outgrowth by inhibition of neovascularization, the SDF-1/CXCR4 pathway seems to be crucial for tumor angiogenesis mediated by HCs and EPCs." (PMID 21977032, 2012). "In contrast with the large number of studies in human oncology, there are only few scientific articles supporting the role of SDF-1/CXCR4 axis in spontaneous tumours of domestic animals." (PMID 22417013, 2012). "The identification of CXCR7 has added new perspectives for the implication of the CXCR4/CXL12 pair in tumor biology." (PMID 22916293, 2012).
tumor (continued). "In fact, CAFs elevate CXCL12 secretion, which in turn can stimulate proliferation and migration of CXCR4-expressing cancer cells in the tumor microenvironment." (PMID 22481918, 2012). "Instead, the tumor infiltrating FoxP3+ T cells highly express memory/tumor-associated CCR8 and CXCR4." (PMID 22292042, 2012). "In GBM, the expression levels of both SDF-1 and its receptor correlate positively with tumor grade, with CXCR4 being mainly localized to tumor endothelial cells, which likely use the SDF-1/CXCR4 axis to migrate during angiogenesis." (PMID 22539956, 2012). "Currently, after having demonstrated anti-tumor activity in pre-clinical and animal tumor models, several CXCR4 antagonists are being evaluated in clinical studies for treatment of patients with hematological and solid tumors." (PMID 23249693, 2012). "Despite all the challenges and drawbacks, tumor stroma remained as the most desirable target for molecular imaging and therapy for cancer management, as new targets like CXCR4 and uPA/uPAR systems are getting additional interest." (PMID 22685650, 2012). "It has been established that the SDF-1—CXCR4 axis promotes the chemotaxis not only of normal but also of tumor cells." (PMID 22496978, 2012). "CXCR4, while expressed by FoxP3+ T cells of both tissues, was better expressed by tumor-infiltrating FoxP3+ T cells." (PMID 22292042, 2012). "Secondly, primary tumor and metastatic tissues from the orthotopic model were examined for CXCR4- and HER2-expression." (PMID 23082154, 2012). "Therefore we hypothesized that HGF induces Rac recruitment at ruffling sites, which may prolong the membrane expression of CXCR4/Rac-1, and reduce the CXCR4 endocytosis caused by chemoattractants and/or CXCR4 antibodies, thereby stimulating the chemotaxis and migration of tumor cells." (PMID 22242160, 2012). "Double-staining for SDF-1 and CXCR4 confirmed their expression in an increasing gradient toward the tumor periphery, as well as in a decreasing gradient away from the tumor in the peritumor host brain tissue." (PMID 22539956, 2012). "CXCR4 overexpression correlated with worse prognosis in patients and constitutive activation of CXCR4 in poorly metastatic ER-positive MCF7 cells led to enhanced tumor growth and metastasis." (PMID 22295247, 2012). "The SDF-1/CXCR4 axis has been recently shown to be involved in stimulating multiple metastatic processes in many different neoplasms, including migration, invasion, angiogenesis and proliferation." (PMID 22200669, 2012). "IGROV-1 cells mock-transfected or transfected with shRNA to CXCR4 were injected i.p. and peritoneal tumour colony formation was assessed over a 6-week time period using intravital and confocal microscopy." (PMID 22322968, 2012). "Currently, increasing evidence has suggested the pivotal role of the SDF-1/CXCR4 biological axis in tumor invasion and metastasis." (PMID 23039915, 2012). "As CD133 has been considered to be a cancer stem cell marker in several tumor types, we examined mRNA expression of the stemness gene Oct-4, NANOG and metastasis-associated receptor CXCR4 using RT-PCR in the CD133+ population and its counterpart CD133− cells." (PMID 23181114, 2012). "The levels of CXCL12 and CXCR4 mRNA in the primary tumor, paracancerous tissues, normal pancreas and lymph nodes surrounding the pancreas were assessed using RT-PCR." (PMID 23181100, 2012). "Although under AMD3100 treatment, CXCR4 expression of the primary tumor is elevated to high levels, CXCR4 expression of metastases matches the expression of the primary tumor and does surpass it." (PMID 23082154, 2012). "The protein kinase C family (PKC) has been shown to be involved in the expression and function of CXCR4, and is also linked to HGF-induced intracellular signal transduction in tumor cells." (PMID 22242160, 2012). "Our findings argue in favor of a specific role of CXCR4 expressed in stromal cells that condition the pro-tumor microenvironment." (PMID 22399057, 2012).